UCK2 (uridine-cytidine kinase 2)
Diseases named in the same sentence as UCK2 in open-access papers (continued):
Sharing a sentence is not in itself a finding about the gene and the disease.
tumor (33 papers, 2008 to 2026). "We have observed that UCK2 plays pivotal roles in prognosis and tumor immunity, and it is associated with DNA repair and cancer stemness." (PMID 39931080, 2025). "Overall, this illustrates that the higher expression of UCK2 is associated with a higher tumor stemness score, stronger the activity of tumor stem cells, and lower the degree of tumor differentiation." (PMID 39931080, 2025). "Clinically, higher UCK2 expression in iCCA tumor was associated with aggressive tumor features, poorer survival and lower sensitivity of chemotherapy." (PMID 39179560, 2024). "Downregulation of UCK2 induced cell cycle arrest and activated the TNFα/NFκB signalling pathway-related senescence-associated secretory phenotype to modify the tumour microenvironment." (PMID 36447138, 2022). "In fact, some previous studies have demonstrated close association between tumor UCK2 levels and objective response to those cytotoxic ribonucleoside analogs." (PMID 35669416, 2022). "Here, we found that UCK2 expression was elevated in iCCA tissues, especially in chemo-resistant iCCA tissues, and high UCK2 expression was associated with aggressive tumor features and poor prognosis, indicating UCK2 show potential to be biomarker in predicting prognosis of iCCA patients." (PMID 39179560, 2024). "Immunohistochemistry (IHC) was utilized to validate the expression of UCK2 in different types cancers using tumor tissue chips." (PMID 39931080, 2025). "we find that gene UCK2 is closed related to RNA stemness scores (RNAss) and DNA stemness scores (DNAss), which is measured the tumor stemness." (PMID 39931080, 2025). "As depicted in heatmaps, UCK2 exhibited a positive correlation with genes related to five gene families in different tumor types, namely ACC, KICH, PCPG, KIRC, and UVM." (PMID 39931080, 2025). "The rationale for the use of UCK2 as a target for cancer therapy is that it is expressed at a high level in tumor cells and relatively low in normal tissues." (PMID 39931080, 2025). "Inhibiting UCK2 directly disrupts the nucleotide “supply” for tumor cells, making it an attractive therapeutic target." (PMID 41357200, 2025). "The HCC tumor size and UCK2 genes expression were significantly alleviated and decreased, respectively, by treatments of anti-PD1 antibody." (PMID 38694506, 2024). "The tumor weight and tumor volume was markedly higher in UCK2-overexpression group than the control group." (PMID 39179560, 2024). "We then measured the expression of UCK2 in 70 iCCA tumor tissues and matched adjacent liver tissues by immunohistochemistry (IHC) staining and found that UCK2 expression were higher in iCCA tumor tissues than matched adjacent liver tissues (P < 0.001)." (PMID 39179560, 2024). "Significant decreases of tumor UCK2 expression was found in the anti-PD1 treated mice compared to the untreated mice." (PMID 38694506, 2024). "According to the qPCR results, UCK2 (uridine-cytidine kinase 2) was highly expressed in almost all 20 tumour specimens from HCC patients; therefore, we further explored the function and mechanism of this gene." (PMID 38896142, 2024). "Previous studies have reported a close relation between tumor UCK2 expression and the objective response to those cytotoxic ribonucleoside analogs." (PMID 39179560, 2024). "The tumor weight and tumor volume was markedly lower in UCK2-knockdown group than the control group." (PMID 39179560, 2024). "The results showed that the expression levels of ADK, ADSL, ATIC, DPYS, ENTPD2, TXNRD1, and UCK2 in at least one tumor cell line were consistent with the predictions." (PMID 37999212, 2023). "Immune cell infiltration level and immune-related functional scores were evaluated to assess the link between tumour microenvironment and UCK2." (PMID 36447138, 2022). "In this mini-review, we introduced the genomic localization and protein structure of UCK2, described the role of UCK2 in tumor development, and discussed the application of UCK2 in anti-tumor treatment." (PMID 35669416, 2022).
tumor (continued). "Considering the results of UCK2-related cancer research, we assessed the expression of UCK2 in 32 tumours, including HCC." (PMID 36447138, 2022). "UCK2 is frequently upregulated in various tumour types and serves as an indicator of poor prognosis." (PMID 36447138, 2022). "A relationship between the gene expression of UCK2 and tumour stemness features was detected on the basis of gene expression data from TCGA-LIHC dataset." (PMID 36447138, 2022). "The GSEA results showed that gene sets related to the cell cycle and mTORC1 signalling pathway were enriched in patients with high levels of UCK2, suggesting a role for UCK2 in tumour progression." (PMID 36447138, 2022). "Gene expression of UCK2 was strongly related to the RNAss signature, suggesting that UCK2 is involved in the transcriptional regulation of tumour stemness." (PMID 36447138, 2022). "UCK1 and UCK2 show a sequence similarity of 72%, and UCK2 has a higher catalytic efficiency than UCK1, indicating that UCK2 is an ideal target for tumour treatment." (PMID 36447138, 2022). "UCK1 is ubiquitously expressed in several tissues, whereas UCK2 is expressed in the human placenta and tumour tissues." (PMID 36447138, 2022). "The mean integral optical density (IOD/Area) values of CENPA and UCK2 were significantly upregulated in the tumor tissues (P < 0.0001)." (PMID 35359370, 2022). "We found that UCK2 was responsive to TGFβ1 stimulation implying the crosslink between microenvironment and tumour cell in the initial stages of tumour formation." (PMID 36447138, 2022). "UCK2 has been reported to be highly expressed in HCC tumors It promotes tumor cell metastasis and invasion through the Stat3 pathway and can be used as an independent prognostic factor." (PMID 33869278, 2021). "NEAT1 expression can be up-regulated in HCC tissues, and NEAT1 can promote the expression of Uridine-Cytidine Kinase 2 (UCK2) by competitively binding to the tumor suppressor miR-199a-3p, so as to maintain the growth of HCC cells." (PMID 34758879, 2021). "Although RNA polymerases are widely expressed in various types of cells, UCK2 is reportedly expressed at a much higher level in tumor cells than in normal cells." (PMID 25087851, 2014). "Low UCK2 activity within tumor tissue would diminish or preclude metabolism of TAS-106 into its active form ECTP and decrease anti-tumor activity." (PMID 23930212, 2013). "We explored differential UCK2 expression between tumor and normal samples." (PMID 39931080, 2025). "UCK2 expression may promote the proliferation and activation of T cells, thereby enhancing the anti-tumor immune response." (PMID 39931080, 2025). "Furthermore, we conducted a comprehensive investigation into the expression of UCK2 on tumor and stromal cells in pan-cancer using the collected cancer single-cell datasets." (PMID 39931080, 2025). "In addition, we compared the expression levels of UCK2 in tumor and paired adjacent normal tissues using TCGA datasets." (PMID 39931080, 2025). "Previous studies have shown that IFNγ can induce tumor stemness, prompting us to explore whether high UCK2 expression drives or results from cancer stemness mediated by IFNγ." (PMID 39931080, 2025). "Therefore, we conducted an analysis of the associations between UCK2 expression and MMR-related genes, HRR signature, and tumor stemness scores (DNA stemness scores and RNA stemness scores." (PMID 39931080, 2025). "Therefore, we conducted an exploration of UCK2 expression in multiple types of cancers, as well as its impact on the tumor immune microenvironment and immunotherapy." (PMID 39931080, 2025). "Furthermore, UCK2 expression levels was higher in tumor tissues than that in normal tissues specimens by western blotting in SYSUCC Cohort." (PMID 39179560, 2024). "DCK and UCK2 in four model genes were highly expressed in the response group which referred to potentially serve as a predictive factor related to the response of tumor immune therapy." (PMID 38517376, 2024).
tumor (continued). "UCK2 were closely associated with cellular sensitivity to TAS-106 and it may contribute to the tumor-selective cytotoxicity of TAS-106." (PMID 39179560, 2024). "Inhibiting the mTOR signalling pathway by rapamycin attenuated the tumour-promoting effect of UCK2." (PMID 36447138, 2022). "In addition, downregulating UCK2 remodelling metabolism in tumour cells can also increase the response to immunotherapy." (PMID 36447138, 2022). "Downregulated UCK2 induced a secretory phenotype, which could improve the microenvironment, and decreased UCK2 remodelling metabolism could lower the resistance of tumour cells to T-cell-mediated killing." (PMID 36447138, 2022). "UCK2 has been reported as a prognostic marker for several tumours, including HCC." (PMID 36447138, 2022). "UCK2 is mainly expressed in tumour tissues and tumour cells." (PMID 36447138, 2022). "Therefore, UCK2 is an ideal target for treating HCC to prevent tumour progression and facilitate immunotherapy." (PMID 36447138, 2022). "UCK2 was positively correlated with the tumour mutation burden (TMB) and microsatellite instability (MSI), which favoured the infiltration of immune effector cells and anti-tumour immune response." (PMID 36447138, 2022). "In addition, the gene expression of UCK2 was significantly positively correlated with all four DNA methylation transferases in different tumour types." (PMID 36447138, 2022). "In the present study, we first explore the link between UCK2 and tumour microenvironment." (PMID 36447138, 2022). "A high level of UCK2 increased the resistance of tumour cells to T-cell cytotoxicity." (PMID 36447138, 2022). "However, UCK2 was negatively correlated with the infiltration of immune effector cells in most tumour types." (PMID 36447138, 2022). "In contrast to UCK2 protein that plays an oncogenic role in tumor progression, a recent study suggested that UCK2 could generate circular RNAs, which may play a tumor suppressive role." (PMID 35669416, 2022). "In addition, four genes (CDC20, UCK2, HEATR6, and SLC9A3R2) were concordantly associated with both survival duration and tumor progression (3.2)." (PMID 34858848, 2021). "UCK2 plays a pro-oncogenic role by promoting tumor cell proliferation and metastasis." (PMID 33277463, 2020). "Animal model experiments confirmed that knocking out UCK2 can inhibit tumour growth in vivo." (PMID 32953265, 2020). "In addition, the present experiment using UCK2 knockdown by siRNA showed that the expression of UCK2 gene in tumour cells was responsible for the enhancement of radiation-induced apoptosis." (PMID 18854835, 2008). "Furthermore, analysis of the CCLE dataset revealed that UCK2 was expressed in all tumor cell lines." (PMID 39931080, 2025). "UCK2 is highly expressed in lymphocytes and may play an important role in the immune system, promoting proliferation in the T cell immune response for effective response to infection or tumor." (PMID 39931080, 2025). "Moreover, increased UCK2 levels in HCC have been shown to promote tumor growth and metastasis by activating critical oncogenic signaling pathways, including STAT3, Wnt/β-catenin, and EGFR-AKT, whereas UCK2 knockdown significantly suppresses tumor cell proliferation." (PMID 41357200, 2025). "This indicates that the UCK2 gene may exerts anti-tumor immunity effects through CD4+ T cells." (PMID 39931080, 2025). "The mechanisms by which UCK2 promotes tumor development may be mainly attributed to its metabolic function by providing sufficient nucleotides to support enhanced DNA and RNA synthesis in tumor cells." (PMID 35669416, 2022). "Moreover, we have demonstrated that the concurrent targeting of the catalytic dependent and independent features of UCK2 could synergistically inhibit tumor growth." (PMID 35669416, 2022). "Moreover, UCK2 expression is high in a number of target tumor tissues." (PMID 27612203, 2016).
tumor (continued). "We conducted an analysis of UCK2 expression using TCGA datasets with normal samples removed, as well as GTEx datasets containing normal samples, CCLE datasets containing tumor samples." (PMID 39931080, 2025). "Studies have shown that UCK2 is related to induction of tumor cell apoptosis, perhaps the apoptosis of MESO and ACC cancer cells is related to the involvement of UCK2, which affects the length of survival through the apoptosis pathway." (PMID 39931080, 2025). "In summary, ICT appears to function through a dual regulatory strategy: “suppressing malignancy” by downregulating pro-oncogenic genes (CA9, UCK2, and FABP5), and “reinforcing physiological function” by upregulating the potential tumor suppressor CYP2C9." (PMID 41357200, 2025). "In addition, UCK2 may also alter the tumor microenvironment by activating the TNF-αNF κB signaling pathway associated with aging secretion phenotype in other cancers, promoting tumor growth and its immune response." (PMID 39931080, 2025). "A significant increase in UCK2, HMMR, and MAGEA6 expression and a significant decrease in CXCL8, EPO, PPARGC1A, FTCD, and CFHR3 expression was observed in tumor tissues." (PMID 38694506, 2024). "Collectively, circUCK2 knockdown repressed tumor growth and metastasis in HCC in vivo via regulating miR-149-5p and UCK2." (PMID 38245591, 2024). "Downregulated UCK2-induced SASP was positively correlated with M1 macrophage infiltration in HCC, promoted anti-tumour immunity and functioned as a biomarker for the immunotherapeutic response." (PMID 36447138, 2022). "EZH2, HMGB3 and UCK2 expressed higher in tumor compared with normal tissues, while NOTCH2 and ODF2 expressed lower in tumor compared with normal tissues." (PMID 32699528, 2020). "More importantly, the xenograft mouse models further validated the synergistic effects of the combined ECyd and Gefitinib treatment in inhibiting tumor growth in MHCC-97L, and in Huh-7 cells overexpressing UCK2." (PMID 33277463, 2020). "For example, the expression of KIF20A, UCK2, and SLC41A3 should be determined in a larger cohort of HCC cell lines with different phenotypes to demonstrate a putative relationship with tumor aggressiveness." (PMID 32382568, 2020). "In particular, UCK2 is preferentially expressed in cancer cells, while UCK1 expression is observed in both cancer and normal cells, explaining the greater anti-tumor effect on cancer cells while sparing normal cells." (PMID 25087851, 2014). "Most notably, in vivo experimental data are currently lacking to confirm whether ICT can similarly modulate the expression of CA9, UCK2, FABP5, and CYP2C9, as well as remodel the tumor immune microenvironment in living organisms." (PMID 41357200, 2025). "UCK2 served as a poor prognostic biomarker for both OS and DFS in several tumour types." (PMID 36447138, 2022). "UCK enzyme activity in two panels of tumor cell lines and xenograft cells correlated only with UCK2-mRNA expression (r = 0.803 and 0.915, respectively), but not with UCK1-mRNA." (PMID 27612203, 2016). "From these six genes two were higher expressed in GAMs derived from the RCAS model (CD300lf and Cd200r4), two genes were expressed at similar levels in GAMs in both tumor models (Trem1 and Sh2d1b1), and two genes were higher expressed in GAMs derived from the GL261 model (Uck2 and Creb5)." (PMID 25658639, 2015). "We also confirmed that the protein expression of UCK2, which is the rate-limiting enzyme required for ECyd activation to exert its anti-tumor effect, was not changed in KB/CDDP(T) when analyzed using immunoblot analysis." (PMID 25087851, 2014). "UCK2 is preferentially expressed in tumor cells compared with normal cells and higher activity of UCK2 has been correlated with TAS-106 sensitivity in tumor cell lines." (PMID 23930212, 2013). "So far, no defined upstream factors have been reported to induce UCK2 expression in tumor." (PMID 35669416, 2022).
tumor (continued). "In addition to the metabolic role, our and other groups have identified the non-metabolic roles of UCK2 in tumor progression, especially in HCCs." (PMID 35669416, 2022). "Interestingly, UCK2 catalytically promotes tumor cell proliferation but non-catalytically enhances tumor cell metastasis." (PMID 33277463, 2020). "However, the link between UCK2 and tumour microenvironment has not been investigated." (PMID 36447138, 2022). "In line with our in vitro findings, the in vivo xenograft model showed that UCK2 knockdown significantly inhibited tumor growth, whereas UCK2WT but not UCK2D62A greatly accelerated tumor growth." (PMID 33277463, 2020).